IL4 (interleukin 4)
Diseases named in the same sentence as IL4 in open-access papers (continued):
Sharing a sentence is not in itself a finding about the gene and the disease.
Allergy (continued). "Moreover, cytokines considered specific to allergy, IL-4, and IL-5 are overexpressed in the ocular surface of DED patients too and another key inflammatory biomarker that can be evidenced in the conjunctiva of DED patients is IL-17 secreted by Th-17 cell." (PMID 37876509, 2023). "Conversely, the M2 feature of several factors (e.g., IL4, 10, 12), despite the immunosuppression, tissue repair, and angiogenesis properties, could induce tumor progression, fibrosis, and allergies." (PMID 37762869, 2023). "IL-4 and IL-13 are mainly involved in type 2 immunity and allergic diseases." (PMID 38074683, 2023). "In order to determine the inhibitory effect on de novo synthesized inflammatory mediators, including TNF-α, IL-6, IL-8, and IL-4 released during an allergic reaction, the HMC-1 cells were pre-treated with KHs for 1 h and followed by a 24 h of induction with PMACI." (PMID 37667314, 2023). "Furthermore, a two-sample MR approach leveraging large GWAS and eQTL databases suggested a potential causal role for IL4, IL1RL1, RP11-13A1.1, FCER1A and MS4A2, RUNX1, and ACLS6 expression in various allergic diseases and serum IgE levels." (PMID 36725846, 2023). "IL-4 is a critical cytokine that controls antibody production, inflammation, and allergy." (PMID 36389843, 2022). "Accordingly, multi-center studies with higher number of ALL patients could be helpful for better understanding the biological role of IL-4 and IgE as well as other allergy-related mediators in the pathogenesis of post-chemotherapy atopy in ALL patients." (PMID 35307016, 2022). "In clinical trials, receiving probiotics has led to the successful control of the immunologic outcomes of allergy (total and allergen specific IgE, leukocyte counts, blood and nasal eosinophils, Th2/Th1 ratio, IL-4 level, thymus-and activation-regulated chemokines, and quality of life)." (PMID 35296330, 2022). "In addition, we observed evidence of intercellular communication via genes implicated in type 2 immunity (CCL11, CCL13, CD5L, IL4, IL5, IL13, IL24) and allergy-linked inflammation (CCL19)." (PMID 35483355, 2022). "In addition, IL-4/IL-4R signaling promotes B cell proliferation and stimulates immunoglobulin class-switching to IgE antibody, the major antibody in allergic reactions." (PMID 35307016, 2022). "Potential targets for developing new therapies for allergic diseases include IgE, TH2 lymphocytes and TH2-derived cytokines, IL-4 and IL-5, and activated mast cells releasing bioactive allergy mediators (histamine, tumor necrosis factor, prostaglandin D2, etc.)." (PMID 35447916, 2022). "Through producing and secreting type 2 cytokines such as IL-4, IL-5 and IL-13, Th2 cells activate B cells to class-switch to IgE and incentive mast cells to release inflammatory mediators, leading to the occurrence of allergic diseases." (PMID 36713372, 2022). "Examples of such genes include IL4 in allergy and TNF in autoimmune diseases." (PMID 35513850, 2022). "Among various Th2 responses in allergic diseases, IL-4/13 are the most well-characterized players." (PMID 36496385, 2022). "A recent study showed that the clinical features of experimental atopic dermatitis are driven by IL-4 and IL-13 signaling via IL-4R and highlighted that IL-4R might serve as a potent therapeutic target for the treatment of AD and other allergic diseases." (PMID 35255962, 2022). "Finally, STAT6 inhibitors are being developed and are logical candidates for allergic disease because of the important role STAT6 plays in IL-4 and IL-13 signaling." (PMID 36230993, 2022). "IL-4 and IL-13 are more important for eliciting allergy than perhaps any other soluble factors." (PMID 36230993, 2022). "IL-4 is a major modulator in the development of IgE-mediated allergies." (PMID 34038479, 2021). "Besides their detrimental role in allergies, IL-4 and IL-13 also play important protective and immunoregulatory functions." (PMID 33976140, 2021).
Allergy (continued). "In addition, basophils can play an IgE independent role in allergies by producing IL-4 in response to other stimuli than the specific allergens." (PMID 34038479, 2021). "IL4 enhances IgE-mediated MC responses and is a necessary mediator of allergy development." (PMID 34130714, 2021). "Our study provides, for the first time, a clear demonstration of the absence of association of the allergy-associated IL4 and FOXP3 polymorphisms with KC in a sample from Western Algerian population." (PMID 34840678, 2021). "FcεRI-mediated MC-derived IL4 production is important for allergy pathogenesis." (PMID 34130714, 2021). "Under inflammatory conditions, such as autoimmune diseases and allergy, it has been shown that several cytokines (IL-4, TNF-α, and IL-6) may be involved in downmodulation of Treg suppression." (PMID 34777330, 2021). "Frequency of detectable IL-4 levels was more common in cases with year round allergy as compared to patients with seasonal allergy (OR = 0.5, P = 0.01), in cases with other co-morbidities (P = 0.02) and patients with all the differential diagnosis of Atopy (P = 0.03)." (PMID 34814942, 2021). "This study compared Th1 (IL-2) and Th2 (IL-4) parameters, anti-inflammatory, pro-inflammatory, or regulatory profile regarding both IgE levels and reported allergies, by means of clinical manifestations and IgE, IL-1β, IL-2, IL-4, IL-17, and TGF-β serum concentration." (PMID 34518597, 2021). "IL-13 and IL-4 genes have been reported to play an important role in allergy." (PMID 34814942, 2021). "In addition, P. cocos extract significantly decreased interleukin (IL-4 and IL-5) secretion by Type 2 T-helper (Th2) cells immune response, which are related to the allergy response." (PMID 33535602, 2021). "IL-4 plays a critical role in the development of Th2 cells and subsequent allergic reactions." (PMID 34444651, 2021). "Increased IL-4 mRNA was also previously identified in BP patients compared to SCZ, and affective disorders may accompany a higher risk of allergic diseases than psychotic disorders." (PMID 33716670, 2021). "Moreover, recent studies have revealed that macrophages, especially alternatively activated macrophages (M2) induced by T helper 2 (Th2) cytokines, such as interleukin (IL)-4 and IL-13, participate in the pathogenesis of allergic diseases." (PMID 33662037, 2021). "However, once Th2 cells developed during an allergic reaction, additional allergen exposure further promotes the production of IL-4 and provides a positive feed-back loop to maintain and/or expand allergen-specific Th2 cells." (PMID 34038479, 2021). "However, inflammatory monocytes can differentiate into M2 macrophages via basophil-derived IL-4 during an allergic reaction." (PMID 34539675, 2021). "IL-4 potentially triggers and sustains mast cells, programs the Th2 cytokine differentiation, and switches B cells to the IgE isotype to induce allergic reactions." (PMID 35222003, 2021). "Studies demonstrated that IL-4 and IL-13, secreted by epithelial cells, lymphocytes, eosinophils, basophils, and mast cells, have a wide range of overlapping but also distinct biological functions, particularly in inflammatory and allergic diseases." (PMID 33804263, 2021). "Furthermore, ferulic acid inhibits TNF-α and IL-4 cytokine levels in IgE-dependent allergic disease experimental models." (PMID 34576749, 2021). "In an in vivo mouse model for ovalbumin (OVA)-induced food allergy, it has been shown that basophils could play an important role in IL-4-related polarization of Th2 cells in the sensitization phase of allergy, which has also been found in vitro." (PMID 32431702, 2020). "Note that the small intestine of the low dose LL treatment group showed a high level of IL4, which might mediate the allergies." (PMID 33379227, 2020). "Furthermore, IL-4 production by MCs and natural killer (NK) T-cells has also been described to play a role in Th2 polarization and allergy." (PMID 32431702, 2020).
Allergy (continued). "In addition, IL-4 mediates and regulates a variety of human host responses, such as allergy, antiparasite response, tumor immunity, and acute inflammation." (PMID 33426089, 2020). "The number of predicted IL-4-inducing peptide segments contained in the tip region of VP2 seems to be positively correlated with the capability to induce the bovine allergy reported in the literature, as well as with the induction of IL-4 expression in the current experimental setting." (PMID 33375108, 2020). "In line with present observations, HDM/DNCB stimulation upregulated the T-bet, STAT3, and GATA3 and other allergy mediating cytokines (IL-4, IL-5, IL-10, IL-13, and IFN-γ) and chemokine (TARC) expression levels, while these were dose-dependently downregulated following SHE treatment." (PMID 32824648, 2020). "Another explanation is that IL17E, also known as IL25, could propagate production of IL-4 and IL-13 in different organs, which stimulate the expansion of eosinophils, and link between allergic disease and psoriatic disease." (PMID 32468320, 2020). "IL-4 increases IgE synthesis in B cells and participates in allergic reactions." (PMID 32408566, 2020). "We hypothesize this could contribute to a downstream decrease in IL-4 producing cells, subsequent induction of allergen tolerance, and elimination of clinical allergic disease." (PMID 32442209, 2020). "Furthermore, IL-4 is considered to play a central role in the perpetuation of IgE - mediated allergic diseases." (PMID 33328996, 2020). "IL-4 is essential cytokine to induce the production of IgE that potentially worsens the symptoms of atopic dermatitis, which is known as a mixed model of the type I and IV allergies." (PMID 31426284, 2019). "Moreover, these oligosaccharides were able to inhibit the secretion of allergy-related mediators like β-hexosaminidase, histamine and IL-4 and TNF-α." (PMID 30988664, 2019). "Given that IL-10 has been reported to cooperate with IL-4 in inducing B cell production of IgG4, and that the latter correlates with allergy desensitization and tolerance, we asked whether CD25+ TF cells could also regulate IgG4 responses." (PMID 31209070, 2019). "In addition, PL or germinated brown rice contains the polyphenolic compounds such as protocatechuic acid and gallic acid, which inhibited the expression of cytokines (TNF-α and IL-4) exerted by IgE-mediated allergy-induced basophils." (PMID 31871471, 2019). "The most pivotal cytokines in an allergic reaction are IL-4 and TNF-α." (PMID 31829185, 2019). "The allergic reaction due to Anisakis has been reported to elicit the host immune response which is characterized by T helper 2 (Th2) response predominantly by secreting cytokines such as interleukin-4 (IL-4) and IL-5." (PMID 31849412, 2019). "In addition, activated RBL-2H3 cells induced the expression of inflammatory cytokines (tumor necrosis factor-α and interleukin-4), which are critical for the pathogenesis of allergic disease, through the activation of c-Jun N-terminal kinase (JNK)." (PMID 31195760, 2019). "Similarly, after feeding Lactobacillus rhamnosus (L. rhamnosus) MTCC 5897 to OVA allergy mice, serum IL-4 decreased, whereas serum IFN-γ increased." (PMID 31143780, 2019). "However, PBMCs from allergy patients produce increased levels of Th2-type cytokines including IL-4, IL-5, and IL-13." (PMID 31826046, 2018). "IL-4 also has an important role in allergy and immunoglobulin class switching." (PMID 29795573, 2018). "Tissue hypereosinophilia occurs with increased IL-4, IL-5, and IL-13 production in B-cell lymphoma 6 (Bcl6)-knockout (KO) mice, suggesting that Bcl6 participates in allergy pathogenesis and that it may be important for reducing TH2 immune responses." (PMID 29696026, 2018). "Moreover, chitin and AMCase have been shown to influence macrophage activation and the accumulation of IL-4 expressing innate immune cells in allergy models." (PMID 29892291, 2018).
Allergy (continued). "These effector-TH2 cells express higher level of IL4, IL5, and IL-9 compared with “classical” TH2 cells and thus could represent pathogenic cells mediating allergy through the IL-33–ST2 signaling pathway." (PMID 29988522, 2018). "Furthermore, allergy immunotherapy inhibited the increasing of IL-25 and Th2 cytokines IL-4, IL-5 and IL-13 with induction of CD4+CD25+ Foxp3+ Treg cells." (PMID 29784924, 2018). "The most recent work advances our understanding of the complex signaling pathways controlling allergic inflammation and paves the way for targeted manipulation of the IL-4/IL-13 pathway in the quest for additional therapeutic interventions against allergic diseases." (PMID 29868002, 2018). "Unfortunately, IL-4 is also a major contributor to the symptoms observed with allergy and asthma." (PMID 29755466, 2018). "This knowledge on IL-4 has growing clinical importance, as therapeutic approaches targeting the cytokine and its signal transduction are becoming a part of the clinical practice in treating allergic diseases." (PMID 29930549, 2018). "Alternative activation of macrophages due to Th2 responses (e.g., IL-4 and IL-13) has been shown to promote fungal persistence, allergy, and disease relapse, and neutralization of endogenous IL-4 has beneficial effects on the survival of mice systemically infected with C. albicans." (PMID 28119468, 2017). "This study suggests IL-5 produced in response to parasite infection may mediate a major part of the protection from autoimmunity and allergy by activation of antigen-specific Treg that have been activated by IL-4." (PMID 29163523, 2017). "Prenatal cigarette smoke exposure could induce thymus atrophy in the fetus and result in allergy-prone deviation in the T-cell response, which manifests as increased IL-4 production during allergic disease development, in postnatal life." (PMID 29212186, 2017). "In addition, mast cells are the sources of several cytokines like pro-inflammatory interleukins (IL1β, TNFα and IL6), interleukins related to tissue repair and allergy (IL4, IL5 and IL13), chemokines (CXCL8 and CCL2) and the growth factor VEGF." (PMID 29232822, 2017). "Th2 cells produce IL-4 and IL-6, which participate in atopic and allergic reactions." (PMID 29383139, 2017). "An increase in Th2 cells leads to increased IL-4 production and leads to increased response to environmental antigens such as pollen, animal dander, and house dust mites and to the development of major symptoms of allergic diseases." (PMID 28904961, 2017). "The in vitro results indicated that La with the capacity to inhibit IL-4 production could have a better anti-allergy effect in vivo than two others." (PMID 27764153, 2016). "In this regard, TH2 cell-derived cytokines such as IL-4, IL-5, and IL-13 play a critical role in the pathogenesis of allergic reaction; IL-4 and IL-13 stimulate IgE production, and IL-5 is responsible for eosinophil growth, differentiation, migration, activation, and survival." (PMID 27376063, 2016). "Notably, Th2 cells produce interleukins 4, 5, 10, 13, and 31 (IL-4, IL-5, IL-10, IL-13, and IL-31) and regulate immune responses involving extracellular pathogens as well as allergic diseases." (PMID 28116316, 2016). "We identified seven cytokines from previous glioma or allergy literature (IL4, IL13, IL5, IL6, IL10, IFNG and TGFB2) to determine whether, they were associated with glioma before diagnosis." (PMID 26352148, 2015). "The suggestive DMRs in this study highlight immune dysfunction through the enrichment of not just immune pathways in general, but to those important to allergic disease, including IL-4 signaling, NFAT regulation of immune response, CD28 signaling in Th cells, and so on." (PMID 26642056, 2015). "IL-4, a pleiotropic cytokine mainly produced by activated Th2 cells, basophils, and mast cells, is an important stimulus for the switching of antibody isotype to IgE, which is often found in patients with allergic diseases." (PMID 25960757, 2015).
Allergy (continued). "If the Th2 cytokine IL-4 is additionally present during B cell activation, class switching is skewed toward the production of IgE molecules, which play an important role in the development of allergies and reactive airway disease." (PMID 25063296, 2014). "The present results showed an important association between SNPs in cytokine genes and susceptibility to or protection from allergy to dust mites in IL1A at position −889, IL4RA at position +1902, IL2 at positions −330 and +166, IL4 at position −590, and IL10 at position −592." (PMID 25238536, 2014). "Th2 cells, with IL-4 as the major cytokine, are important for the production of immunoglobulin, clearance of extracellular organisms, and protection against helminthes; in addition, they are responsible for the pathogenesis of allergic diseases." (PMID 24558316, 2014). "The secretion of IL-4 from eosinophils in local tissues during allergic reactions may serve as a major initial source of IL-4 required for switching tissue-infiltrating naïve T cells to the Th2 phenotype." (PMID 25426119, 2014). "In addition to histamine, conjunctival mast cells express and release the proinflammatory cytokines tumor necrosis factor (TNF)-α, interleukin-4 (IL-4), and IL-13 during acute allergic reactions." (PMID 23878502, 2013). "Also, we showed that MP treatment decreased Th2 cytokine IL-4, which plays a central role in the promotion of an allergic inflammatory eosinophilic reaction in allergic diseases through IgE isotype switching." (PMID 23997805, 2013). "IL-4 is synthesized by Th2 cells and plays an important role in allergic reactions." (PMID 23843865, 2013). "The role of Th17 cells and Th17 cytokines in allergic diseases is still unclear; however, some studies have indicated that Th17 cells may be involved in inhibiting the production of the Th2 cytokines, IL-4 and IL-5." (PMID 23346203, 2012). "IL-10 is a key regulator of allergic diseases, not only because it downregulates the Th2 cell-derived cytokines IL-4 and IL-5, but also because it directly inhibits the IgE-induced degranulation of mast cells, which leads to a reduced secretion of the inflammatory mediator histamine." (PMID 23346203, 2012). "Although we have focused on TH1 responses, the same approach could also be applied using different reporters to the sensitive detection of antigen-specific TH2 cells involved in allergy (e.g. IL-4 or 5 induced genes) and IL-10 or IL-17 secreting T cells." (PMID 21853018, 2011). "Our studies show the importance of IL-4 and IL-5 cytokines in response to allergy." (PMID 20616938, 2010). "IgE mediated allergy is promoted by T-helper (Th) 2 lymphocytes producing IL-4, IL-5 and IL-13." (PMID 19900263, 2009). "In allergic diseases, IL-4-controlled transcriptional regulatory processes might be physiologically regulated by dual molecules, including activators such as STATs and repressors such as BCL6." (PMID 23282478, 2008). "We hypothesize that therapeutic agents aimed at neutralizing IL-4 could be a novel strategy to facilitate inducible Treg cell generation and thus promotion of tolerance in allergies and other Th2-dominated diseases." (PMID 18162042, 2007). "The development of most immune diseases depends on the cytokines interleukin-2 and interferon-γ produced by type 1 helper T cells (Th1), whereas the development of allergic diseases requires IL-4 and IL-5, both of which are produced by type 2 helper T cells (Th2)." (PMID 15710045, 2005). "Because our results show that CD4+ T cells from a mouse model of allergy could still differentiate into Tregs under appropriate conditions of limited IL-4 and IFN-γ production, we consider that regulation of the cytokines may be useful for designing treatments using iTregs." (PMID 40446078, 2025). "Thus, the higher levels of IL-4, IL-10 and IL-33 found in DK may reflect the higher prevalence of allergies typically seen in high-income countries (HIC) compared to low- and middle-income countries (LMIC)." (PMID 40338935, 2025).